GHSR (growth hormone secretagogue receptor)
Diseases named in the same sentence as GHSR in open-access papers (continued):
Sharing a sentence is not in itself a finding about the gene and the disease.
tumor (42 papers, 2007 to 2026). "Diagnostic performance of the marker panel GHSR/MAL was also higher in primary than in recurrent tumours." (PMID 35123558, 2022). "The diagnostic performance of the GHSR/MAL marker panel was also better in primary tumours than in recurrent tumours." (PMID 35955727, 2022). "Growth hormone secretagogue receptor (GHSR) is expressed in a variety of peripheral organs, the brain, and tumor tissues, making it an important molecular target for both translational imaging and mechanistic studies of GHSR-related physiology and pathology." (PMID 41982719, 2026). "Bladder tumours have a higher mass at primary diagnosis than at recurrence, resulting in a superior sensitivity of the GHSR/MAL marker panel in primary tumours." (PMID 35955727, 2022). "Urine pellet represented the respective tumour tissues best, it reached the highest discriminative capability for the marker panel GHSR/MAL, and it was the most convenient to process." (PMID 35123558, 2022). "Growth hormone secretagogue receptor (GHSR) is activated by Ghrelin that has a key role in tumor progression." (PMID 37303943, 2021). "For patients with T3 and T4 tumor sizes with a methylated GHSR promoter, the OR was 1.95 (95% CI: 1.17–3.24; P = 0.010)." (PMID 31974445, 2020). "GHSR promoter methylation was the most accurately detected (with AUROC of 0.81 obtained from the ROC) in tumor samples and matched paired normal mucosal samples." (PMID 31974445, 2020). "Accordingly, the increase in tumor size was slighter in NOD/SCID mice injected with GHSR-1a knock-out Ishikawa cell line compared to mice receiving intact Ishikawa cell line." (PMID 31681567, 2019). "Ghrelin is a hormone that acts via growth hormone secretagogue receptor (GHS-R), which is overexpressed in many neoplasms and is involved in tumorigenesis." (PMID 29262839, 2017). "They found atractylodin enhanced the ghrelin-induced Ca2+ fluorescence in GHSR-expressing cells, prolonged the survival of tumor-bearing rats, and alleviated age-related diseases in klotho-deficient, SAMP8, and aged ICR mice." (PMID 28883883, 2017). "It is well-documented that tumor-bearing rats and aged mice can be treated with atractylodin by activating GHSR." (PMID 28883883, 2017). "Consistent with the high sensitivity of hypermethylation at the GHSR locus, all four tumor samples demonstrated intermediate to dense DNA methylation at this locus." (PMID 18091988, 2007). "At the molecular level, our bioinformatics analysis results suggested that HTR2C, TACR3, MCHR2 and GHSR might be LINC01296 targets through tumor microenvironment and phosphorylation regulation." (PMID 34515611, 2021). "Besides, atractylodin has been used to treat tumor-bearing rats and aged mice, being related to GHSR." (PMID 28883883, 2017). "As expected, methylation of GHSR was the optimal single biomarker, resulting in an overall average error rate of 8.3% (16 of 103 tumors were misclassified as normal, and 1 of 104 normals was misclassified as tumor)." (PMID 18091988, 2007). "Mechanistically, low BMI activates ghrelin-GHSR signaling, increasing neuronal neuropeptide Y (NPY) secretion, which promotes tumor metabolic reprogramming via NPY-Y5R, facilitating brain colonization." (PMID 40595538, 2025). "Sensitivity of GHSR/MAL increased with higher tumour grades, higher tumour stages, in primary vs. recurrent tumours, and in males vs. females." (PMID 35123558, 2022). "In full void, methylation levels of GHSR, miR-129, PRDM14, SST and ZIC1 were significantly correlated to the matched tumor tissues." (PMID 32252299, 2020). "Strikingly, our study identified a single locus within the promoter region of the GHSR gene that is hypermethylated in 54.3% (151 of 278) of HNSCC, independently of patient age or tumor stage." (PMID 31974445, 2020). "Among 135 cases with T1 and T2 tumor sizes, the DFS rates in those with GHSR and NMUR1 methylated genes were compared to the unmethylated group (log-rank test, P = 0.418 and P = 0.031, respectively)." (PMID 31974445, 2020).
tumor (continued). "Studies have shown that GHSR-1b is capable of heterodimerizing with GHSR-1a and promoting translocation, thereby blocking downstream signaling transduction; however, this functionality does not explain its role in tumor progression." (PMID 35454071, 2022). "It is very intriguing that GHSR-1b, but not GHSR-1a, is overexpressed in many tumor types, including breast, neuroendocrine, adrenocortical tumors, prostate, and colorectal cell lines." (PMID 35454071, 2022). "Nevertheless, none of the studies published to date using ghrelin or GHSR-1a agonists in mice or humans have shown an increase in tumor progression." (PMID 32934774, 2020). "This was more prominent in the absence of GHSR-1a, suggesting a protective role of this endogenous pathway in tumor-bearing animals." (PMID 32934774, 2020). "As an example, a truncated isoform of GHSR1a, the GHSR type 1b (GHSR1b), is found in the majority of the tumors and cancer cell lines cited above, however, its potential role in tumor regulation remains unknown." (PMID 21829727, 2011). "Lastly, we used a global GHSR-1a KO line in the current study, which may limit our understanding of tissue- and developmental-specific differences, and the LLC tumor model, although well-characterized and native to our mouse strain, has a high tumor burden compared to human disease." (PMID 32934774, 2020). "So far, we have performed experimental validation on four of the identified candidates (GLIPR1L1, GHSR, CEACAM6, and CCR9, of which we here report on CCR9) using additional tumor cell lines and antigen-specific CTL clones and in all cases we could confirm their immune-modulatory function." (PMID 25691366, 2015). "It is an endogenous ligand of the growth hormone secretagogue receptor (GHS-R) and binds to different GHS-R subtypes in peripheral tissues to regulate physiological functions such as energy metabolism, gastrointestinal function, tumor cell proliferation, cardiovascular function, and hormone release." (PMID 26713091, 2015). "The marker panel GHSR/MAL did not miss any of the muscle-invasive tumours and only two of the non-invasive HG/G3 tumours." (PMID 35123558, 2022). "We tested the effect of LLC tumor cell implantation with and without exogenous ghrelin administration in GHSR-1a WT (Ghsr+/+) and KO (Ghsr−/−) mice using heat-killed (HK)-LLC cells-inoculated mice of both genotypes as negative controls." (PMID 32934774, 2020). "Although administration of des-acylated ghrelin did not affect tumor volume in mice with PC3 cell xenograft, GHSR antagonist [D-Lys 3]-GHRP-6 reduced the tumor volume." (PMID 31681567, 2019).
metabolic disorders (14 papers, 2014 to 2025). "Whether the striking effects of exogenous LEAP2 in humans will revitalize the GHSR as a therapeutic target in metabolic diseases awaits further studies." (PMID 35492241, 2022). "The observed effects on both glucose homeostasis and appetite regulation may revitalize the GHSR as therapeutic target in metabolic diseases in the future." (PMID 35492241, 2022). "Hence, this limits the effects of the exploration on blockage of ghrelin including inactivation and the use of GHSR antagonists in treatment of metabolic disorders." (PMID 30405536, 2018).
infection (5 papers, 2022 to 2025). The state of being infected such as from the introduction of a foreign agent such as serum, vaccine, antigenic substance or organism. "Additionally, the expression of MyD88, NF-κB p65, iNOS, and Arg-1 was significantly elevated in the E. granulosus group, confirming that GHSR-/- mice exhibited milder infection and a lower inflammatory status, further supporting the conclusion that GHSR deficiency alleviates E. granulosus infection." (PMID 40065480, 2025). "In contrast, the GHSR−/− group maintained a Th1/Th2 immune balance similar to that of normal mice, which correlated with a milder infection and reduced immune activation." (PMID 40065480, 2025). "In the present study, we found that the serum Ghrelin levels were significantly reduced in E. g-infected mice during the late stage of infection and showed a significant negative regulatory relationship with liver GHSR." (PMID 39436864, 2024). "GHSR gene knockout may improve the progression of liver E. granulosus infection and the liver inflammation induced by infection." (PMID 40065480, 2025). "However, the serum Ghrelin levels were significantly elevated in E. g-infected mice during the early stage of infection, and protein expression of Ghrelin and GHSR was also significantly elevated in and around liver lesions." (PMID 39436864, 2024). "However, whether GHSR inhibition can reduce its expression and inhibit the infection process remains unexplored, necessitating further in vivo studies to determine its precise role and potential therapeutic effects in the infection process." (PMID 40065480, 2025). "We aimed to investigate whether genetic knockout of the ghrelin receptor GHSR could improve disease progression in liver E. granulosus infection and mitigate liver inflammation induced by infection." (PMID 40065480, 2025). "The results indicated that GHSR protein levels continuously decreased throughout the infection, highlighting a negative correlation between Ghrelin and total liver receptor protein levels, consistent with previous studies." (PMID 39749332, 2024). "Therefore, downregulation of GHSR during early infection stage may not be helpful to the resolution of pro-inflammatory, thereby increasing the helminth impact on host fitness." (PMID 35320269, 2022).
psychiatric disorder (5 papers, 2014 to 2024). A disorder characterized by behavioral and/or psychological abnormalities, often accompanied by physical symptoms. "This preliminary study also revealed that GHSR is associated with SA in our Mexican population with psychiatric disorders." (PMID 31578828, 2019). "This complicates the evaluation of pathological relevance and therapeutic utility of ghrelin and GHSR in stress-related psychiatric disorders." (PMID 33192444, 2020).
bacterial infection (2 papers, 2021 to 2022). "The effect of bacterial infection on the expression of growth hormone secretagogue receptor (GHS-R) was investigated in periodontal cells and tissues, and the actions of ghrelin were evaluated." (PMID 35328456, 2022).
neurodegenerative disease (2 papers, 2023 to 2025). A disorder of the central nervous system characterized by gradual and progressive loss of neural tissue and neurologic function. "Thus, future work into the mechanisms underlying the pro‐neurogenic effects of GHSR signalling may reveal new therapeutic targets for age‐related decline and neurodegenerative diseases." (PMID 37987211, 2023). "Conversely, ghrelin exhibits an inhibitory effect on other brain cell types expressing GHSR, such as astroglia and microglia, to protect neurons from the adverse effects of pro-inflammatory factors released during neurodegenerative disease or injury processes." (PMID 40595538, 2025).
adenocarcinoma (1 paper, 2012). A common cancer characterized by the presence of malignant glandular cells. "The expression of ghrelin and growth hormone secretagogue receptor at mRNA level was detected in adenocarcinomas of the 1st, the 2nd and the 3rd grade of malignancy (total n = 18)." (PMID 22999388, 2012).
heart disease (1 paper, 2025). "Therefore, changes in the distribution of myocardial GHSR appear to be associated with cardiac pathology in both mouse models and in human heart disease." (PMID 40643523, 2025). "Our group has developed novel fluorescent analogs of GHSR ligands to reveal changes in the dynamics of myocardial GHSR during cardiomyocyte differentiation, in a mouse model of diabetic cardiomyopathy, and in human myocardial tissue before and after cardiac transplantation and heart disease." (PMID 40643523, 2025).
GHSR also shares sentences with these, for which no sentence is quoted: gastric cancer (8 papers); Alzheimer disease (7); Hypertension (4); ileus (4); myocardial infarction (4); eating disorder (3); epilepsy (3); neuroblastoma (3); nicotine addiction (3); pituitary adenomas (3); viral infection (3); age (2); anorexia nervosa (2); Arrhythmia (2); cardiovascular disease (2); endocrine pancreatic tumor (2); Glucose intolerance (2); hypothyroidism (2); Impaired glucose tolerance (2); insulinomas (2); memory impairment (2); morbid obesity (2); neuroendocrine tumor (2); neurofibroma (2); overnutrition (2); pancreatic cancer (2); periodontitis (2); Stroke (2); acute myeloid leukemia (1); acute respiratory distress syndrome (1).
A further 71 diseases each share a sentence with GHSR in 1 paper.